DCSTAMP (dendrocyte expressed seven transmembrane protein)
Description:
Probable cell surface receptor that plays several roles in cellular fusion, cell differentiation, bone and immune homeostasis. Plays a role in TNFSF11-mediated osteoclastogenesis. Cooperates with OCSTAMP in modulating cell-cell fusion in both osteoclasts and foreign body giant cells (FBGCs). Participates in osteoclast bone resorption. Involved in inducing the expression of tartrate-resistant acid phosphatase in osteoclast precursors. Plays a role in haematopoietic stem cell differentiation of bone marrow cells toward the myeloid lineage. Inhibits the development of neutrophilic granulocytes. Plays also a role in the regulation of dendritic cell (DC) antigen presentation activity by controlling phagocytic activity. Involved in the maintenance of immune self-tolerance and avoidance of autoimmune reactions.
Synonyms: DC-STAMP; hDC-STAMP; FIND; TM7SF4
Tractability: Antibody: UniProt places it where antibodies can reach, with medium confidence; UniProt predicts a signal peptide or a membrane-spanning region; its Gene Ontology location is reachable by antibodies, with medium confidence.
Gene: Protein-coding gene on chromosome 8 (104,339,087 to 104,356,689, forward strand). Ensembl gene ENSG00000164935.
Subcellular location: Cell membrane; Endoplasmic reticulum membrane; Endoplasmic reticulum-Golgi intermediate compartment membrane; Endosome
Pathways (Reactome):
Cellular responses to stimuli: CREB3 factors activate genes
Gene Ontology:
Molecular function: protein binding
Biological process: cellular response to interleukin-4; cellular response to macrophage colony-stimulating factor stimulus; cellular response to tumor necrosis factor; membrane fusion; myeloid dendritic cell differentiation; negative regulation of cell growth; osteoclast differentiation; osteoclast fusion; positive regulation of bone resorption; positive regulation of macrophage fusion; positive regulation of monocyte differentiation
Cellular component: cell surface; endoplasmic reticulum membrane; endosome membrane; membrane; endoplasmic reticulum-Golgi intermediate compartment membrane; endosome; plasma membrane
Genetic constraint (gnomAD): Loss-of-function variants: 25 observed, 34.82 expected, observed/expected ratio (o/e) 0.72, 90% interval 0.52 to 1. The upper end of that interval is the gene's LOEUF score, 1, which puts it in group 4 of 6, group 1 being the genes least tolerant of losing a copy. Missense variants: 531 observed, 585.5 expected, observed/expected ratio (o/e) 0.91, 90% interval 0.84 to 0.97. Synonymous variants: 245 observed, 227.55 expected, observed/expected ratio (o/e) 1.08, 90% interval 0.97 to 1.2.
Homologues: Orthologues: chimpanzee DCSTAMP (99% identical), macaque DCSTAMP (95% identical), dog DCSTAMP (78% identical), pig DCSTAMP (78% identical), mouse Dcstamp (74% identical), rat Dcstamp (73% identical), guinea pig DCSTAMP (70% identical), tropical clawed frog dcstamp (31% identical). Paralogues in human: DCST1 (19% identical), DCST2 (19% identical), OCSTAMP (16% identical).
Diseases named in the same sentence as DCSTAMP in open-access papers:
DCSTAMP is named in the same sentence as 20 diseases in open-access papers, as found by Europe PMC text mining. Sharing a sentence is not in itself a finding about the gene and the disease. The quoted sentences say what the papers report.
osteoporosis (7 papers, 2017 to 2025). A condition of reduced bone mass, with decreased cortical thickness and a decrease in the number and size of the trabeculae of cancellous bone (but normal chemical composition), resulting in increased fracture incidence. "Our current investigation using Mendelian randomization revealed a potential inverse correlation between human osteoclast DCSTAMP expression and eBMD, further demonstrating DCSTAMP as a therapeutic candidate for osteoporosis intervention." (PMID 41423555, 2025).
Paget disease (3 papers, 2015 to 2020). A malignant neoplasm composed of large cells with large nuclei, prominent nucleoli, and abundant pale cytoplasm (Paget cells). "Another SNP in the DCSTAMP gene, rs62620995, was also found to be linked with Paget’s disease and osteoclasts generated from carriers of this SNP specifically gained more nuclei per osteoclast than non-carriers." (PMID 33086479, 2020). "This is of special interest, as OC-like cells derived from patients with Paget’s disease, carrying a nonsynonymous coding variant in their DCSTAMP gene, display an increased number of nuclei compared to cells derived from healthy controls." (PMID 32887359, 2020). "Given that Paget’s disease is a condition where multinucleation of osteoclasts is out of control, it is interesting that precisely the DCSTAMP gene contains a SNP (rs2458413) that can trigger this condition." (PMID 33086479, 2020).
Paget’s disease of bone (3 papers, 2017 to 2022). "DCSTAMP is a seven-pass transmembrane protein expressed by dendritic cells and associates with some diseases such as Paget's disease of bone." (PMID 35675043, 2022).
thyroid cancer (2 papers, 2015 to 2023). "Eleven of 18 BRAFV600E-specific genes were previously reported as related to thyroid cancer, with 6 documented as associated with BRAF mutation (DCSTAMP, MET, FN1, DIO1, EPHA2, and ERBB3)." (PMID 26625260, 2015).
viral myocarditis (1 paper, 2024). Myocarditis that is caused by an infection with a viral agent. "We also identified two positively selected genes (MYH6 and DCSTAMP) specific to Chinese serow, which were involved in 'viral myocarditis' and 'Cardiac muscle contraction'." (PMID 39385836, 2024).
DCSTAMP also shares sentences with these, for which no sentence is quoted: osteopetrosis (7 papers); tumor (4); Autoimmunity (3); cancer (2); acute myeloid leukemia (1); Arthritis (1); atherosclerosis (1); autoimmune disease (1); bone disorder (1); giant cell tumor (1); Obesity (1); rheumatoid arthritis (1); sarcoidosis (1); synovitis (1); thyroid tumor (1).